BDNF (brain derived neurotrophic factor)
Diseases named in the same sentence as BDNF in open-access papers (continued):
Sharing a sentence is not in itself a finding about the gene and the disease.
Tinnitus (continued). "As BDNF levels were higher in the right (contralateral) IC than in the left IC, regardless of receiving rTMS or sham, our results suggest acoustic trauma itself may affect BDNF, suggesting possible BDNF involvement in the generation of tinnitus." (PMID 27905540, 2016). "Analyses of BDNF expression suggest that BDNF signalling mechanisms are not strongly linked to LI-rTMS-induced alleviation of behavioural signs of tinnitus, but BDNF levels may be affected by acoustic trauma." (PMID 27905540, 2016). "We examined whether low intensity rTMS (LI-rTMS) alleviates signs of tinnitus in a guinea pig model and whether this involves changes in BDNF expression and hyperactivity in inferior colliculus." (PMID 27905540, 2016). "We also investigated a possible mechanism by which LI-rTMS could influence tinnitus, by measuring hyperactivity in IC and brain-derived neurotrophic factor (BDNF) levels in IC and auditory cortex." (PMID 27905540, 2016). "Brain-derived neurotrophic factor (BDNF) (rs6265) may, potentially, be an indicator of susceptibility for tinnitus distress, and the catecholo-methyl-transferase (COMT) polymorphism may be associated with tinnitus loudness." (PMID 39989649, 2024). "New technologies may enable to re-evaluate the possible link between BDNF and tinnitus." (PMID 38079022, 2023). "Fourth, we did not include a control group in the present study as it did not reflect the research aim; therefore, no information is available on whether hair-cortisol and hair-BDNF levels were altered in our chronic tinnitus sample compared to healthy individuals." (PMID 35121746, 2022). "This suggests that antagonizing the BDNF signaling pathway after cochlear lesion may counteract the mechanisms resulting in central hyperactivity and potentially those involved in the generation of tinnitus and hyperacusis." (PMID 27630564, 2016). "An audiological study of the psychological impact of tinnitus in adults found increased levels of the stress hormone cortisol in hair, cortisol concentration (HCC) measurements, along with decreased levels of brain derived neurotrophic factor (BDNF)." (PMID 39831149, 2025). "While our panels did not include proteins such as IL-1β or BDNF, our analysis suggest that IL-10 plays no role in constant tinnitus." (PMID 38079022, 2023). "In models without imputation of tinnitus matching data, tinnitus loudness was still identified as a predictor for both hair-cortisol and hair-BDNF, but the effects were smaller, especially for hair-BDNF." (PMID 35121746, 2022). "In one study on GDNF and BDNF gene SNPs, there was no allelic association between two BDNF SNPs (rs6265, rs2049046) and three GDNF SNPs (rs1110149, rs884344, rs3812047) in patients with chronic subjective tinnitus." (PMID 34205595, 2021). "This suggests that LI-rTMS alleviates behavioural signs of tinnitus by a mechanism independent of inferior colliculus hyperactivity and BDNF levels and opens novel therapeutic avenues for tinnitus treatment." (PMID 27905540, 2016). "Analysis revealed a significant reduction of tinnitus after LI-rTMS compared to sham, without a statistical significant effect on BDNF levels or hyperactivity." (PMID 27905540, 2016). "The LI-rTMS treatment did not affect BDNF levels in IC or auditory cortex and so this molecule does not seem to be involved in the mechanism by which LI-rTMS affects tinnitus." (PMID 27905540, 2016). "To date, hair-cortisol and hair-BDNF have not been studied in tinnitus." (PMID 35121746, 2022). "Together with the lack of a correlation between hair-BDNF and tinnitus loudness, the validity of the effect of tinnitus loudness on hair-BDNF may be limited." (PMID 35121746, 2022). "For hair-cortisol, no influencing factor could be identified; for hair-BDNF, relationships with hearing threshold, tinnitus loudness, and tinnitus-related distress appear relevant." (PMID 35250657, 2022).
Tinnitus (continued). "Our finding that low-frequency LI-rTMS does not strongly affect BDNF levels in auditory structures in a guinea pig model of tinnitus suggests that LI-rTMS effects may be brain-region specific and/or dependent on the presence of injury." (PMID 27905540, 2016).
behavioral disorders (21 papers, 2011 to 2025). "It is been suggested that uneven levels of pro-BDNF and mature BDNF cause the neuronal death and behavioral disorders." (PMID 36217471, 2022). "While an interfering peptide that blocked the formation of Pdcd4-eIF4A complex substantially promoted BDNF expression and corrected the behavioral disorders which were caused by CRS." (PMID 32203159, 2021). "Reduced BDNF expression levels are associated with cognitive and behavioral disorders in neurological disorders, such as cerebral malaria." (PMID 32843073, 2020). "Importantly, administration of Pdcd4 siRNA or an interfering peptide that interrupts the Pdcd4-eIF4A complex substantially promoted BDNF expression and rescued the behavioral disorders which were caused by CRS." (PMID 32203159, 2021). "Previous studies support the role of BDNF in regulating the response to stress and behavioral disorders." (PMID 39607287, 2024). "These behavioral disorders caused oxidative stress damage in the hippocampus and changes in NLRP3, IL‐1β and BDNF levels." (PMID 39443283, 2024). "Accumulating evidence has demonstrated that the cross-talk between the BDNF and brain 5-HT system is involved in the development of behavioral disorders." (PMID 38473717, 2024). "There is a large amount of evidence for the role of BDNF in the pathogenesis of behavioral disorders." (PMID 36187803, 2022). "A strong relationship between BDNF, neural plasticity, and behavioral disorders has been demonstrated." (PMID 35624812, 2022). "Brain-derived neurotrophic factor (BDNF) is member of nerve growth factor family that has a structural role in neuronal development and function that is closely related to mood and behavioral disorders in many conditions." (PMID 35622593, 2022). "Lycopene has been shown to improve dextran sulfate sodium induced colitis depression and behavioral disorders via balancing the microbiota–gut–brain axis balance by upregulating BDNF expression and postsynaptic density protein." (PMID 36499295, 2022). "The BDNF rs6265 was shown to correlated with the development of OCD, ADHD and behavioral disorders, which confirms a possible association with ICD (19582215)." (PMID 34945793, 2021). "Reduced BDNF levels and altered BDNF signaling have been reported in several brain diseases and behavioral disorders, which also exhibit reduced levels of AMPAr subunits." (PMID 23460828, 2013). "The relationship between BDNF and behavioral disorders has been demonstrated in many studies." (PMID 35624812, 2022). "TrkB is a specialized receptor of BDNF which decrease is observed in behavioral disorders." (PMID 31924200, 2020). "At the same time, SDFs were found to improve synaptic plasticity in the brain by modulating the level of BDNF and sphingolipid-related metabolite, thereby preventing behavioral disorders, which suggests that gut–brain axis homeostasis may also be the underlying mechanism." (PMID 40077572, 2025). "As BDNF has an important role in neural plasticity and neuronal protection in several brain regions, including the olfactory bulb, this could have important health implications regarding the development of behavior disorders and neurodegenerative disease." (PMID 33371327, 2020). "Previous studies have publicized that damage to the BDNF, tropomyosin receptor kinase B (TrkB), or cyclic adenosine monophosphate responsive element-binding protein (CREB) pathway can result in neurological and behavioral disorders." (PMID 31924200, 2020). "In addition, evidence of oxidative damage pathways may contribute to behavioral disorders found but not BDNF expression." (PMID 36355545, 2022).
stress-related disorder (21 papers, 2010 to 2025). Stress-related disorders are mental health disorders that are a result of an atypical response to both short and long-term anxiety due to physical, mental, or emotional stress. "Stress exposure reduces BDNF expression in rodent models leading to high susceptibility for the development of stress-related disorders." (PMID 40656087, 2024). "Since in animal models a decreased Brain-Derived Neurotrophic Factor (BDNF) expression and/or function, particularly in hippocampus, have been implicated in the pathophysiology of stress-related disorders, we explored such a relationship." (PMID 26501066, 2014). "Our observations are in line with two recent studies demonstrating that mice susceptible to stress-related disorders after chronic social defeat have an overactivity of BDNF/TrkB signaling in their reward system." (PMID 20333308, 2010). "In addition, patients suffering from stress-related disorders display decreased levels of BDNF, and its expression has strongly been implicated in antidepressant activity." (PMID 33344707, 2020). "This cross-sectional study aimed to evaluate the pBDNF and BDNF promoters’ DNA methylation levels in workers exposed to occupational stress and suffering from work-related stress disorders." (PMID 39595869, 2024). "This review addresses the effects of ELS paradigms on GC- and BDNF-dependent mechanisms and their crosstalk in the hippocampus, including potential implications for the pathogenesis of common stress-related disorders." (PMID 26635521, 2015). "However, for human studies and the less-specific peripheral BDNF measurements, the literature overwhelmingly converges on neuroprotective effects, especially in relation to stress-related disorders." (PMID 39896238, 2025). "BDNF is the main neurotrophin in the adult brain, mediating neuronal development and synaptic function, and it is extensively studied for its central role in stress-related disorders and the mechanism of antidepressants." (PMID 37445990, 2023). "In stress-related disorders, depletion of serotonin reduces brain BDNF levels." (PMID 31905199, 2020). "Reduced neurogenesis and a lack of neurotrophic support, such as that reflected in reduced plasma brain-derived neurotrophic factor (BDNF) levels, as well as increased stress hormones are consistent findings in stress-related disorders, including PTSD." (PMID 28851339, 2017). "While citalopram primarily enhances serotonin availability, JSO appears to influence both neuroinflammation and neuroplasticity, as indicated by its effects on BDNF and synaptic proteins, such as PSD-95 and SYP, which are crucial for synaptic health and resilience in stress-related disorders." (PMID 39555096, 2024). "Building on these findings, our research focused on the dynamics of DNA methylation of the candidate genes, BDNF, COMT, and SLC6A4, involved in the pathophysiology of stress-related disorders, i.e., pathways involved in neurotransmitter systems and neuroplasticity." (PMID 37754245, 2023).
cystitis (20 papers, 2013 to 2025). Inflammation of the urinary bladder. "To investigate the underlying mechanisms and pathways that regulate BDNF expression in the sensory neurons, we utilized a visceral inflammatory model with cystitis that was induced by intraperitoneal injection of CYP." (PMID 24303055, 2013). "Real-time PCR examination showed that cystitis also caused an increase in BDNF mRNA level in the L6 DRG." (PMID 24303055, 2013). "Further study of ketamine cystitis will need to address whether the cause of nerve fascicle hyperplasia is the direct action of ketamine and/or its metabolites; or alternatively, whether circulating BDNF could be the causative agent." (PMID 24252413, 2013). "An upregulation of BDNF expression was evident in the CYP-constructed cystitis model, in contrast to the control group." (PMID 40064496, 2025). "BDNF is also upregulated in micturition reflex pathways in both humans and rodents with cystitis because of increased NGF synthesis." (PMID 37811396, 2023). "A possible explanation is increased retrograde transport of BDNF to the dorsal root ganglia and spinal dorsal horn at later time points in cystitis, contributing to central windup." (PMID 37701182, 2022). "BDNF is upregulated throughout the micturition pathway in both humans and rodents with cystitis as a consequence of increased NGF synthesis and its reduction is associated with subjective improvement in IC/BPS patients undergoing treatment." (PMID 37701182, 2022). "Increased NGF and BDNF expression in the urinary bladder with CYP-induced cystitis has been demonstrated in preclinical animal models and human patients with IC/BPS." (PMID 35528149, 2022). "Body parameters such as BW, BMI, and BFP among all our chronic pain patients showed comparably higher data than our HSs, who showed a higher amount of BDNF." (PMID 33915758, 2021). "Our results provide evidence that BDNF promotes activation of astrocytes and microglia to release TNF-α and IL-1β contributing to aggravating the neuroinflammation and mechanical allodynia through BDNF-TrkB-p38/JNK signaling in CYP-induced cystitis." (PMID 31931832, 2020). "In this investigation, we present novel evidence showing how astrocytes and microglia activated to increase neuroinflammation and mechanical allodynia in our CYP-induced cystitis model through BDNF-TrkB-p38/JNK signaling." (PMID 31931832, 2020). "In our CYP-induced cystitis model, BDNF promoted the activation of astrocytes and microglia to release TNF-α and IL-1β, aggravating neuroinflammation and leading to mechanical allodynia through BDNF-TrkB-p38/JNK signaling." (PMID 31931832, 2020). "Consistent with this previous finding, BDNF sequestration improved voiding function in rats with chronic cystitis." (PMID 25951823, 2015). "In this treatment regimen, we found that prevention of endogenous Akt activity by LY294002 also blocked cystitis-induced BDNF protein and mRNA up-regulation in L6 DRG." (PMID 24303055, 2013). "Treatment with NGF neutralizing antibody also decreased the BDNF mRNA level in CYP-treated animals when compared to CYP+IgG treatment, suggesting that endogenous NGF elicited BDNF transcription in the L6 DRG during cystitis." (PMID 24303055, 2013). "We showed above that endogenous NGF increased BDNF expression in L6 DRG during cystitis, and NGF also activated Akt in L6 DRG." (PMID 24303055, 2013). "The primary sensory projection of the urinary bladder in rat lies in the lower lumbar segment thus this study specifically addresses changes in the L6 DRG during cystitis and mainly focuses on mechanistic regulation of BDNF in L6 DRG in vivo." (PMID 24303055, 2013). "These in vivo and in vitro experiments indicated that NGF played an important role in the activation of Akt and subsequent up-regulation of BDNF in the sensory neurons in visceral inflammation such as cystitis." (PMID 24303055, 2013).
cystitis (continued). "BDNF up-regulation in the L6 DRG was triggered by endogenous nerve growth factor (NGF) because neutralization of NGF with a specific NGF antibody reduced BDNF levels during cystitis." (PMID 24303055, 2013). "The PI3K-Akt-BDNF axis was regulated by endogenous NGF in cystitis and also by retrograde NGF signaling in culture." (PMID 24303055, 2013). "The other pathway that is likely involved in BDNF up-regulation in the DRG during cystitis is the ERK5 pathway." (PMID 24303055, 2013). "In cystitis, BDNF action in the spinal cord induces ERK activation; the latter has been demonstrated to increase in the spinal cord and has roles in cystitis-induced bladder hyperactivity." (PMID 24303055, 2013). "Here we used a rat model of cystitis and found that the mRNA and protein levels of BDNF were increased in the L6 dorsal root ganglia (DRG) in response to bladder inflammation." (PMID 24303055, 2013). "In cyclophosphamide (CYP)-induced cystitis, intrathecal injection of either a general Trk receptor antagonist or a BDNF scavenger reduces bladder hyperactivity and also reduces spinal extracellular signal-regulated kinase (ERK) phosphorylation." (PMID 24303055, 2013). "In the present study, we show that BDNF mRNA and protein levels are also increased in cystitis, a painful inflammatory condition of the urinary bladder." (PMID 24303055, 2013). "BDNF sequestration improves bladder function in rats with chronic cystitis, and the BDNF/creatinine ratio is significantly higher in OAB patients compared to controls." (PMID 24152577, 2013). "For example, microglial activation was identified in spinal cord of EAP mice and associated with increased brain-derived neurotrophic factor (BDNF) expression, and spinal dorsal horn microglia were similarly activated in mice treated with cyclophosphamide to induce cystitis." (PMID 35980963, 2022). "Since we confirmed that CYP-induced cystitis overexpressed BDNF-TrkB signaling, we conducted some follow-up experiments to explore whether blocking the BDNF-TrkB signaling could alleviate the onset of allodynia in the cystitis model." (PMID 31931832, 2020). "In a drug-induced cystitis animal study, the authors showed that systemic intraperitoneal injection of cyclophosphamide induced upregulation of BDNF-TrkB signaling, activation of astrocytes and microglia, and several proinflammatory cytokines in the spinal dorsal horn of rats." (PMID 32664974, 2020). "The conjecture that BDNF may promote activation of astrocytes and microglia to contribute to aggravating neuroinflammation and mechanical allodynia of CYP-induced cystitis through BDNF-TrkB signaling is the first time to be proposed." (PMID 31931832, 2020). "Thus it is likely that in cystitis the elevated level of NGF in the inflamed urinary bladder can increase BDNF expression in the DRG through retrograde transport." (PMID 24303055, 2013). "To examine whether cystitis-induced BDNF up-regulation in L6 DRG was triggered by endogenous NGF in vivo, we administered a NGF neutralizing antibody to rats with cystitis to block NGF action." (PMID 24303055, 2013). "To examine whether NGF-induced Akt pathway had a role in NGF-induced BDNF expression during cystitis, we first compared the expression pattern of BDNF and p-Akt." (PMID 24303055, 2013). "We found that activation of the PI3K/Akt pathway led to BDNF up-regulation in the DRG in cystitis." (PMID 24303055, 2013). "In addition, BDNF sequestration improved bladder function in rats with chronic cystitis." (PMID 24614892, 2014). "NGF may play a role in regulating BDNF in sensory neurons in cystitis." (PMID 24303055, 2013). "In conclusion, by regulating the BDNF–TrkB signaling, EA nerve stimulation can effectively alleviate bladder dysfunction and mechanical allodynia in the CYP-induced cystitis model." (PMID 40064496, 2025).